ZNF169 (zinc finger protein 169)
Description:
May be involved in transcriptional regulation.
Synonyms: MGC51961
Tractability: No criterion of Open Targets' tractability assessment is met for any kind of drug.
Gene: Protein-coding gene on chromosome 9 (94,259,298 to 94,303,967, forward strand). Ensembl gene ENSG00000175787.
Subcellular location: Nucleus
Subcellular location (Human Protein Atlas): Nuclear speckles; Cytosol
Pathways (Reactome):
Gene expression (Transcription): Generic Transcription Pathway
Gene Ontology:
Molecular function: protein binding; DNA-binding transcription factor activity, RNA polymerase II-specific; RNA polymerase II transcription regulatory region sequence-specific DNA binding
Biological process: regulation of transcription by RNA polymerase II; regulation of DNA-templated transcription
Cellular component: nucleus
Genetic constraint (gnomAD): Loss-of-function variants: 11 observed, 12.05 expected, observed/expected ratio (o/e) 0.91, 90% interval 0.57 to 1.5. The upper end of that interval is the gene's LOEUF score, 1.5, which puts it in group 6 of 6, group 1 being the genes least tolerant of losing a copy. Missense variants: 722 observed, 783.06 expected, observed/expected ratio (o/e) 0.92, 90% interval 0.87 to 0.98. Synonymous variants: 302 observed, 301.16 expected, observed/expected ratio (o/e) 1, 90% interval 0.91 to 1.1.
Homologues: Orthologues: chimpanzee ZNF169 (98% identical), macaque ZNF169 (97% identical), pig ZNF169 (77% identical), dog ZNF169 (75% identical), mouse Zfp169 (64% identical), rat Zfp169 (64% identical), Drosophila melanogaster CG3281 (22% identical), Drosophila melanogaster Phs (20% identical), Drosophila melanogaster CG2712 (20% identical). Paralogues in human: ZNF875 (52% identical), ZNF133 (52% identical), ZNF343 (45% identical), ZNF337 (44% identical), PRDM9 (41% identical), ZNF805 (36% identical), ZNF25 (35% identical), ZNF264 (35% identical), ZNF599 (34% identical), ZFP90 (34% identical), ZNF614 (34% identical), ZFP37 (33% identical), and 50 more.
Diseases named in the same sentence as ZNF169 in open-access papers:
ZNF169 is named in the same sentence as 5 diseases in open-access papers, as found by Europe PMC text mining. Sharing a sentence is not in itself a finding about the gene and the disease. The quoted sentences say what the papers report.
Obesity (1 paper, 2017). Accumulation of substantial excess body fat. "Of these GPGE association results, BARX1, ZNF169 and FAR1 were all significant in brain regions, which is consistent with a popular hypothesis that the central nervous system regulation of energy balance plays a major role in the development of obesity." (PMID 28417008, 2017).
osteosarcoma (1 paper, 2025). A usually aggressive malignant bone-forming mesenchymal neoplasm, predominantly affecting adolescents and young adults. "In osteosarcoma, FAM106A has been reported to trans-regulate the coding gene AL023806.1 through the transcription factor ZNF169." (PMID 41387767, 2025).
cardiovascular disease (1 paper, 2021). "Seven genes overlap with these regions, and interesting examples include ZNF169, involved in the immune-related pathways and associated with body mass index, and HHAT, associated with cardiovascular disease and lung function." (PMID 34716342, 2021).
tumor (1 paper, 2026). "Vaccination with mutant peptides ZNF169-A275S and CDH4-V456M inhibited tumor growth in an autologous humanized CRC mouse model." (PMID 42087894, 2026).
ZNF169 also shares sentences with these, for which no sentence is quoted: glioma (1 paper).